RCN2 (reticulocalbin 2)
Description:
Not known. Binds calcium.
Synonyms: E6BP; ERC55; ERC-55; TCBP49
Tractability: Antibody: UniProt predicts a signal peptide or a membrane-spanning region. PROTAC: ubiquitination databases record sites on it; its protein half-life has been measured.
Gene: Protein-coding gene on chromosome 15 (76,931,738 to 76,954,393, forward strand). Ensembl gene ENSG00000117906.
Subcellular location: Endoplasmic reticulum lumen
Subcellular location (Human Protein Atlas): Endoplasmic reticulum
Gene Ontology:
Molecular function: protein binding; calcium ion binding
Cellular component: endoplasmic reticulum; endoplasmic reticulum lumen
Genetic constraint (gnomAD): Loss-of-function variants: 15 observed, 18.29 expected, observed/expected ratio (o/e) 0.82, 90% interval 0.55 to 1.26. The upper end of that interval is the gene's LOEUF score, 1.26, which puts it in group 5 of 6, group 1 being the genes least tolerant of losing a copy. Missense variants: 269 observed, 243.05 expected, observed/expected ratio (o/e) 1.11, 90% interval 1 to 1.22. Synonymous variants: 110 observed, 91.98 expected, observed/expected ratio (o/e) 1.2, 90% interval 1.02 to 1.4.
Homologues: Orthologues: chimpanzee RCN2 (100% identical), mouse Rcn2 (93% identical), rat Rcn2 (92% identical), dog RCN2 (91% identical), pig RCN2 (90% identical), guinea pig RCN2 (88% identical), macaque RCN2 (85% identical), rabbit RCN2 (82% identical), tropical clawed frog rcn2 (60% identical), zebrafish rcn2 (46% identical), Caenorhabditis elegans cex-1 (14% identical). Paralogues in human: CALU (37% identical), RCN1 (37% identical), RCN3 (35% identical), SDF4 (24% identical).
Diseases named in the same sentence as RCN2 in open-access papers:
RCN2 is named in the same sentence as 27 diseases in open-access papers, as found by Europe PMC text mining. Sharing a sentence is not in itself a finding about the gene and the disease. The quoted sentences say what the papers report.
cervical cancer (3 papers, 2020 to 2023). A primary or metastatic malignant neoplasm involving the cervix. "Upregulation of RCN2 facilitates cell malignant behaviors and angiogenesis in cervical cancer and hepatocellular carcinoma." (PMID 37723418, 2023).
colorectal cancer (3 papers, 2021 to 2025). A primary or metastatic malignant neoplasm that affects the colon or rectum. "Cox's proportional hazards analysis showed that high RCN2 expression was an independent prognostic marker of poor outcome in colorectal cancer." (PMID 37723418, 2023). "Knockdown of RCN2 inhibited colorectal cancer cell proliferation both in vitro and in vivo." (PMID 37723418, 2023). "RCN2 also enhances the proliferation and invasion of colorectal cancer cells." (PMID 37723418, 2023). "Reticulocalbin-2 (RCN2) was validated to elicit an oncogenic function in colorectal cancer." (PMID 34774078, 2021).
hepatocellular carcinoma (3 papers, 2021 to 2023). A malignant tumor that arises from hepatocytes. "Increased RCN2 level plays a vital role in hepatocellular carcinoma (HCC) proliferation, invasion and migration and predicted poor prognosis in HCC patients." (PMID 37723418, 2023). "As an example, RCN2 was unveiled to be up-regulated in hepatocellular carcinoma (HCC) and its expression was positively correlated with tumor size in HCC patients." (PMID 34774078, 2021).
Hypertension (3 papers, 2022 to 2024). The presence of chronic increased pressure in the systemic arterial system. "The human RCN2 gene is located in a chromosomal region where genetic variants are associated with blood pressure or hypertension." (PMID 35406670, 2022). "Previous research has indicated that RCN2 is a candidate gene for atherosclerosis, contributing to vascular remodeling in hypertension." (PMID 39742022, 2024). "Deletion of the Rcn2 gene lowers blood pressure and attenuates angiotensin II-induced hypertension in mice." (PMID 35406670, 2022).
atherosclerosis (2 papers, 2022 to 2024). A disease characterized by the build-up of fatty material and calcium deposition in the arterial wall resulting in partial or complete occlusion of the arterial lumen. "Atherosclerosis-susceptible C57BL/6 (B6) mice had higher plasma Rcn2 levels than resistant C3H mice." (PMID 35406670, 2022). "This study showed that atherosclerosis-susceptible B6-Apoe−/− mice had higher plasma Rcn2 levels than resistant C3H-Apoe−/− mice before and after two weeks on the Western diet." (PMID 35406670, 2022). "In contrast, blood RCN2 levels appeared to be more specific and related to atherosclerosis and risk factors." (PMID 35406670, 2022). "We evaluated the potential of circulating RCN2 to identify subjects with or at risk of developing atherosclerosis." (PMID 35406670, 2022). "Patients with atherosclerosis and mice susceptible to atherosclerosis had elevated serum or plasma RCN2 levels." (PMID 35406670, 2022). "Plasma Rcn2 levels of two Apoe−/− mouse strains with different atherosclerosis susceptibility." (PMID 35406670, 2022). "Thus, in the present study, we examined whether circulating RCN2 in the blood could differentiate human subjects with atherosclerosis or at high risk of developing atherosclerosis from those without atherosclerotic risk." (PMID 35406670, 2022). "Meanwhile, further evidence supports that the upregulation of RCN2 in atherosclerosis, as well as the ability of IL-1A to mitigate the progression of atherosclerosis, can both serve as potential biomarkers for CAD." (PMID 39742022, 2024). "This study suggests that circulating RCN2 is a potential non-invasive biomarker for identifying individuals with atherosclerosis and HDL protects against atherosclerosis by downregulation of RCN2 expression in endothelial cells." (PMID 35406670, 2022). "We found that serum RCN2 concentrations were significantly elevated in patients with atherosclerosis in comparison with healthy individuals." (PMID 35406670, 2022). "This study suggests the potential of circulating RCN2 as a novel biomarker for identifying individuals with atherosclerosis." (PMID 35406670, 2022). "Therefore, compared with healthy samples, serum or plasma RCN2 levels in atherosclerotic patients and mice prone to atherosclerosis are increased." (PMID 39742022, 2024). "Thus, atherosclerotic plaques probably contributed to elevated serum RCN2 concentrations in patients with atherosclerosis." (PMID 35406670, 2022). "Given that atherosclerosis is a multifactorial chronic disease, the enhancement of low K+ to RCN2-mediated inflammation could be pathologically significant in vivo." (PMID 35406670, 2022). "Elevated serum RCN2 levels in patients with atherosclerosis." (PMID 35406670, 2022). "Considering that atherosclerosis is the main pathological basis of CAD, circulating RCN2 may become a new biomarker for identifying individuals with CAD." (PMID 39742022, 2024). "Expression of Rcn2 in arteries with and without atherosclerosis." (PMID 35406670, 2022).
breast carcinoma (2 papers, 2020 to 2023). "In breast cancer cells, RCN1 forms a complex with PIGX and RCN2 that negatively regulates the expression of ZIC family member 1 (ZIC1) and EH domain‐containing protein 2 (EHD2), promoting breast carcinogenesis." (PMID 37746742, 2023).
nasopharyngeal carcinoma (2 papers, 2023). A carcinoma arising from the nasopharyngeal epithelium. "In nasopharyngeal carcinoma, RCN2 curbed mitochondrial apoptosis and interacted with CALR25." (PMID 37735575, 2023).
age (1 paper, 2023). A temporal measurement of the time period elapsed since an identifiable point in the life cycle of an organism. "RCN2 promotes bone formation by promoting lipolysis, and supplementation of RCN2 recombinant proteins can alleviate load loss as well as age-related bone loss." (PMID 39872060, 2023).
cognitive decline (1 paper, 2026). "Knockdown of hippocampal RCN2 directly led to cognitive decline and synaptic damage." (PMID 41987460, 2026).
colon adenoma (1 paper, 2023). An adenoma that arises from the colon. "In Sabates-Bellver’s dataset, RCN2 was found highly expressed in rectal adenoma with a fold change of 2.174, and in colon adenoma with a fold change of 2.198 versus normal samples." (PMID 37723418, 2023).
epilepsy (1 paper, 2022). A brain disorder characterized by episodes of abnormally increased neuronal discharge resulting in transient episodes of sensory or motor neurological dysfunction, or psychic dysfunction. "Given the critical role of GABAA receptors in the pathophysiology of epilepsy, it will be of great interest to determine how RCN2 regulates GABAA receptor biogenesis and contributes to epilepsy phenotypes in the future." (PMID 36030824, 2022).
head and neck cancer (1 paper, 2023). A primary or metastatic malignant neoplasm affecting the head and neck. "Additionally, RCN2 play a similar function in cancer progression and present similar prognostic features for NPC from GEO (GSE102349) database, and head and neck cancer (HNSC) from The Cancer Genome Atlas (TCGA) database." (PMID 36952101, 2023).
lymphoma (1 paper, 2025). A malignant (clonal) proliferation of B- lymphocytes or T- lymphocytes which involves the lymph nodes, bone marrow and/or extranodal sites. "Survival was better in patients in whose lymphomas CD8+ T cell–rich RCN2 neighborhoods were situated less than 400 pixels (133 μm) away from the immune-poor RCN5 neighborhoods (5-year PFS: 87.8% vs. 65.7%, P = 0.039)." (PMID 40772779, 2025). "The proportion of CD8+ T cell–rich RCN2 and immune-poor RCN5 was higher in lymphomas in which these RCNs were situated close to each other (adj." (PMID 40772779, 2025).
Obesity (1 paper, 2025). Accumulation of substantial excess body fat. "To further investigate the genetic evidence linking RCN2 to obesity, we conducted Sanger sequencing to screen for RCN2 variants in 2000 Chinese participants with obesity." (PMID 39875551, 2025). "Moreover, we found that patients with obesity carrying a heterozygous RCN2 nonsense variant had lower Raptin levels during the sleep phase and exhibited evening hyperphagia." (PMID 39875551, 2025). "Thirdly, we found that individuals with RCN2 nonsense variant suffered from obesity." (PMID 39875551, 2025). "Moreover, humans carrying an RCN2 nonsense variant present with night eating syndrome and obesity." (PMID 39875551, 2025). "To test whether hypothalamus-derived Raptin is involved in SF-induced obesity, we overexpressed Rcn2 in the PVN of SF mice." (PMID 39875551, 2025). "Notably, we identified a heterozygous RCN2 nonsense variant that co-segregated with obesity within a specific family, as indicated by this RCN2 variant observed in the proband with obesity (II2) and two other family members with obesity (II3 and III2) but not in other family members." (PMID 39875551, 2025).
osteoporosis (1 paper, 2025). A condition of reduced bone mass, with decreased cortical thickness and a decrease in the number and size of the trabeculae of cancellous bone (but normal chemical composition), resulting in increased fracture incidence. "Hui Peng found that mechanical stimuli induced by exercise promote the release of reticulocalbin-2 (RCN2) from macrophages, thereby stimulating bone marrow adipocyte metabolism and alleviating osteoporosis." (PMID 41153709, 2025).
thyroid cancer (1 paper, 2023). "Analysis of TCGA Database reveals elevation of RCN2 and the expression of RCN2 protein in HNSC was second only to thyroid cancer among the 20 different types of tumors." (PMID 36952101, 2023).
viral infection (1 paper, 2025). "Beyond viral infection, RCN2 has been linked to several cancers, including HCC, where its expression is typically increased in contrast to the reduction observed during HBV infection." (PMID 41201845, 2025).
tumor (9 papers, 2005 to 2025). "The subcutaneous tumors in the knockout RCN2 group had a smaller volume and weighed less than those in the control group, while RCN2 overexpression was associated with a significant increase in tumor size and weight." (PMID 36952101, 2023). "The first was a group of novel genes and the second was a group of genes associated with various cancer and tumour diseases (TXNDC12, NRDC, MIR761, ITSN2, NCOA1, SCUBE2, DENND5A, RCN2)." (PMID 40003092, 2025). "We observed that the expression levels of XPO1 and RCN2 were elevated in tumor tissues compared with adjacent-tumor tissues." (PMID 39712016, 2024). "Further analysis indicated that the expression of XPO1 and RCN2 was greater in tumor tissues with high Ki67 expression." (PMID 39712016, 2024). "Mechanistically, MFAP5 deficiency in CAFs downregulates HAS2 and CXCL10 via MFAP5/RCN2/ERK/STAT1 axis, leading to angiogenesis, hyaluronic acid (HA) and collagens deposition reduction, cytotoxic T cells infiltration, and tumor cells apoptosis." (PMID 37156839, 2023). "The five TAAs identified (Tes, Rcn2, Rnf4, Cradd, Galnt3) are those whose expression is linearly related to the tumor mass increase in BALB-neuT mammary glands." (PMID 16351756, 2005). "Next, we investigated the effects of RCN2 on the malignant biological behavior of tumor cells." (PMID 36952101, 2023). "Besides, enhanced RCN2 expression restored the tumor growth in vivo that was inhibited by DUXAP8 repression." (PMID 34774078, 2021). "To better elucidate the impact of MECOM, RCN2, and MBNL3 on the tumor microenvironment and immunotherapy, we conducted an immune infiltration analysis." (PMID 36171401, 2022). "Mechanically, RCN2 overexpression markedly reversed the anti-tumor effects induced by miR-1297 overexpression and DUXAP8 knockdown on CC cells, indicating that DUXAP8 regulated the progression of CC by targeting miR-1297/RCN2 axis." (PMID 34774078, 2021).
cancer (8 papers, 2020 to 2025). A tumor composed of atypical neoplastic, often pleomorphic cells that invade other tissues. "For example, CD44, ARIH2, CSDE1 (also known as UNR), CYB5B, SF3B1, and RCN2, which have been reported to be overexpressed in cancer, showed an increased proportion of shorter 3′-UTRs, primarily as a result of alternative cleavage and polyadenylation (APA)." (PMID 40702779, 2025). "Taken together, these results indicate that RCN2 is involved in the regulation of cancer cell apoptosis under intracellular stress." (PMID 36952101, 2023). "High levels of RCN2 expression in a subset of cancer cells may facilitate cell survival in adverse environments." (PMID 36952101, 2023). "To find potentially approved drugs that target MECOM, RCN2, and MBNL3, we screened the herb database for related small molecules with anti-cancer effects." (PMID 36171401, 2022).
infection (1 paper, 2025). The state of being infected such as from the introduction of a foreign agent such as serum, vaccine, antigenic substance or organism. "It remains unclear whether the reduction of RCN2 represents an active viral mechanism, analogous to HBx-mediated degradation of the Smc5/6 complex, or a secondary consequence of infection-induced stress." (PMID 41201845, 2025).
RCN2 also shares sentences with these, for which no sentence is quoted: adenocarcinoma (1 paper); Alzheimer disease (1); Cognitive impairment (1); diabetes (1); neurodegenerative disease (1); prostate carcinoma (1); rectal adenoma (1).